MCAM (melanoma cell adhesion molecule)
Diseases named in the same sentence as MCAM in open-access papers (continued):
Sharing a sentence is not in itself a finding about the gene and the disease.
melanoma (continued). "In particular, SB-2 melanoma cell lines, commonly characterized by a low metastatic potential, do not regularly express MCAM/MUC18 but, when subsequently transfected with full-length human cDNA MCAM/MUC18 construct and injected in mice, easily develop metastases." (PMID 24902661, 2014). "Whether or not a combination of MCAM, MMP-2, CCPG4, PAX-3, and Gal-3 can identify those thin melanomas that comprise the 5% that will develop metastases at a later stage will require further studies of clinical material." (PMID 24069584, 2013). "MCAM/MUC18 RT-PCR assay, even if not practical for routine melanoma diagnosis due to its low specificity, may improve the accuracy of staging and monitoring a specific subset of melanoma patients." (PMID 24902661, 2014).
breast carcinoma (100 papers, 2005 to 2025). "Overexpression of MCAM in noninvasive epithelial breast cancer cells induced migration and invasiveness associated with upregulation of EMT markers, through the RhoA pathway mediated by Slug." (PMID 41388158, 2025). "Our results show that high levels of MCAM gene expression are associated with poor prognosis in breast cancer because they reflect tumour vascularisation and high levels of EMT." (PMID 37138793, 2023). "In the breast cancer tissues of Trim11+/+ and Trim+/− mice, MCAM expression was down-regulated with Trim11 deficiency." (PMID 36192394, 2022). "A higher expression of MGAM has been noted in luminal A breast cancers, and a meta-analysis identified that MCAM mutations are associated with a positive clinical benefit in non-small lung cancer cases." (PMID 34384498, 2021). "The pro-metastatic role of MCAM/CD146 is further confirmed by the analysis of a human cohort of breast cancer showing that its high expression is associated with worsened prognosis." (PMID 33404012, 2021). "Recently, an MCAM/MUC18/C146 stromal/mesenchymal signature has been described associated with poor prognosis in several cancers, in particular in breast cancer." (PMID 32548126, 2020). "However, increased CD146/MCAM expression is associated with poor prognosis in breast cancer, a characteristic that is difficult to reconcile with inhibition of TEM by CD146 and its epigenetic silencing." (PMID 37138793, 2023). "We analysed the expression of the MCAM gene (encoding CD146) across a panel comprising 42 oestrogen receptor (ER)+ primary breast cancer samples, 42 primary TNBC samples and 56 samples from normal adjacent tissue or non-cancerous breast tissue removed during breast reduction surgery." (PMID 37138793, 2023). "Thus, MCAM/CD146 expression is associated with poor prognosis in breast cancer in at least two ways, increased vascularisation of the tumour and as a marker of EMT of the malignant cells themselves." (PMID 37138793, 2023). "For instance, MCAM was highly regulated in breast cancer, and its downregulation was linked to the suppression of epithelial-mesenchymal transition and chemoresistance in breast cancer cells." (PMID 36340580, 2022). "Importantly, MCAM is associated with poor prognosis in various cancers, including ovarian cancer, and with enhanced motility of melanoblast and breast cancer cells." (PMID 33371469, 2020). "Aberrant CpG island methylation in the MCAM promoter has also been observed in breast cancer cell lines." (PMID 41388158, 2025). "In breast cancer cells, treatment with the demethylating agent 5-aza-2-deoxycytidine led to increased expression of MCAM at both the mRNA and protein levels, indicating that hypermethylation of the MCAM promoter represses its transcription." (PMID 41388158, 2025). "On the other hand, in breast cancer, histone demethylase KDM5C—responsible for demethylating H3K4me3—has been implicated in the transcriptional control of MCAM." (PMID 41388158, 2025). "In the context of breast cancer, an early report published in 1997 suggested a potential role for MCAM as a tumor suppressor." (PMID 41388158, 2025). "Recent data show that MCAM is a key cargo of EVs released by breast cancer cells and plays a crucial role in the EV-dependent seeding of pre-metastatic niches." (PMID 41388158, 2025). "In recent years, some researchers have reported that MCAM‐mediated cell invasion, EMT, and metastasis in breast cancer, while CD146 depletion significantly inhibited T‐cell antitumor response in tumor models." (PMID 40042109, 2025). "We also reported a crucial role of MCAM in breast cancer in response to extracellular S100A8/A9, underscoring the indispensable function of inflammatory cytokines in cancer-associated microenvironments." (PMID 40924339, 2025).
breast carcinoma (continued). "We demonstrate that these seemingly opposing roles for CD146 can be reconciled by considering the intra-tumoural heterogeneity of breast cancer and MCAM expression and the role of EMT in generating MCAM expressing, invasive cells." (PMID 37138793, 2023). "Our results suggest that CD146 expression negatively regulates these events, a conclusion supported by reduced MCAM expression in breast cancer." (PMID 37138793, 2023). "Our data show that MCAM gene expression in breast cancer is indicative of the relative levels of EMT in the tumour sample." (PMID 37138793, 2023). "Expression of MCAM was detected in multiple cell types in breast cancer, including the malignant and normal epithelial cells, as well as other cell types, with high level expression found in EC and PVC." (PMID 37138793, 2023). "Our analysis of MCAM gene expression at the single cell level in breast cancer confirmed high levels of MCAM expression in both EC and PVC." (PMID 37138793, 2023). "Furthermore, we show that a reduction in MCAM gene expression is associated with the increased methylation of the MCAM promoter in tumour tissue, an epigenetic modification that is known to repress gene expression and highlighted as a key regulator of breast cancer progression." (PMID 37138793, 2023). "The ability of cell surface CD146 to inhibit breast cancer TEM is consistent with the reduced expression of the MCAM gene in malignant versus normal breast tissue via epigenetic silencing." (PMID 37138793, 2023). "Our data show that TRIM11 and KDM5C regulate the expression of MCAM in breast cancer cells, through targeting an enhancer close to MCAM TSS." (PMID 36192394, 2022). "As a secretory cytokine, S100A9 accelerates breast cancer growth and metastasis upon binding to a cell surface receptor, melanoma cell adhesion molecule (MCAM)." (PMID 35484101, 2022). "RelA and RelB are able to decrease the levels of MCAM and CD146 adhesion molecules in the release of EVs, leading to breast cancer metastasis." (PMID 35765040, 2022). "In breast cancer, while iCAFs (PDGFRB+, ACTA2-, CD34+, MCAM-) were implicated in cytotoxic T cell dysfunction of tripe-negative breast cancer, myCAFs (ecm) and myCAFs (TGFβ) were shown to be the primary resistance elements of immunotherapies." (PMID 34869001, 2021). "Identical with the results from HPA database, MUC1 expression was significantly upregulated while MUC18 (MCAM) expression was obviously downregulated in breast cancer samples." (PMID 34828282, 2021). "Last, we analyzed the expression of novel breast cancer targets MCAM/CD146 and SOD1 in the cell lines." (PMID 26968831, 2016). "However, more than a decade later, studies contradicted these findings by demonstrating that MCAM expression enhances motility in breast cancer cell lines and characterized it as a “prometastatic factor associated with poor prognosis histoclinical features”." (PMID 41388158, 2025). "This suggested that the reduced expression of the MCAM gene found in patient-derived breast cancer samples might be due to increased promoter methylation." (PMID 37138793, 2023). "Moreover, extracellular S100A8/A9 can regulate breast cancer aggressiveness by inducing EMT via the MCAM/ETV4 axis." (PMID 35936690, 2022). "And their cross-talk regulates hypoxia/reoxygenation (H/R) induces breast cancer progression and further regulates the expression of melanoma cell adhesion molecule (MelCAM) urokinase-type plasminogen activator (uPA) matrix metalloproteinase-9 (MMP-9) and VEGF." (PMID 36226050, 2022). "We recently published an article which showed Notch1 could also transcriptionally activate MCAM in breast cancer cells." (PMID 32636747, 2020). "MCAM has also been implicated in a reciprocal regulatory loop with AKT/PKB (protein kinase b), a molecule that has been associated with increased survival and directional migration in breast cancer cells." (PMID 22272201, 2012).
breast carcinoma (continued). "Finally, we identify the adhesion protein CD146/MCAM as a key EV cargo controlled by RalA and RalB and demonstrate that it conveys, in part, the pro-metastatic function to EVs by controlling the lung tropism of breast cancer EVs." (PMID 33404012, 2021). "Finally, RalA, RalB, and MCAM/CD146, are factors of poor prognosis in breast cancer patients." (PMID 33404012, 2021). "In breast cancer, the increase in H3K36me2 by SMYD2 is involved in upregulating the melanoma cell adhesion molecule (MCAM) gene and regulating the characteristics of cancer stem cells." (PMID 39482529, 2024). "Our efforts have revealed that S100A8/A9 induces the metastatic progression of breast cancer cells upon binding with an S100A8/A9 receptor, i.e., melanoma cell adhesion molecule (MCAM) on cancer cells." (PMID 37091157, 2023). "This is consistent with our in vitro data, whereby reduction of MCAM expression in the MDA-MB-231 cells, a breast cancer cell line with mesenchymal characteristics, enhanced its invasiveness." (PMID 37138793, 2023). "Analysis of patient survival rate with TCGA breast cancer data show that patients with higher MCAM expression have worse survival rate, further supporting that regulation of MCAM by TRIM11 and KDM5C is important for breast cancer." (PMID 36192394, 2022). "Notably, reduced expression of MCAM and CLDN11 in breast cancer correlated with poor overall survival and relapse-free survival." (PMID 40083695, 2025). "Analysis of breast cancer cells revealed that MCAM is highly expressed in ERα-negative breast cancer cell lines, which are generally unresponsive to tamoxifen." (PMID 41388158, 2025). "Studies using breast cancer cell lines (including MDA-MB-231) have demonstrated that the MCAM gene is regulated by promoter methylation and that treatment with demethylating agents enhances MCAM gene expression and expression of CD146." (PMID 37138793, 2023). "Thus, MCAM has been identified as a molecule that influences the regulation of EMT during cancer progression, and for this reason, was called the EMT inducer, specifically in breast cancer." (PMID 41388158, 2025). "MCAM-overexpressing breast cancer cells exhibit increased expression of Slug and downregulation of ERα, suggesting that the MCAM/Slug/ERα axis may contribute to tamoxifen resistance in ERα-negative breast cancer." (PMID 41388158, 2025).
prostate carcinoma (30 papers, 2009 to 2025). A carcinoma that arises from epithelial cells of the prostate gland. "Previous literature indicated that these six genes, i.e., CAV1, COL4A2, HSPB1, ITGB3, MAP1A and MCAM, were linked to prostate cancer progression." (PMID 26158290, 2015). "Given that CD146 (MCAM) was consistently up-regulated in both experimental approaches, we decided to further study its role and significance in prostate cancer." (PMID 40230419, 2025). "In our previous study, MCAM promoter methylation was directly correlated with tumor stage (pT3 + pT4) (P = 0.001) and Gleason score (P = 0.018) in primary prostate carcinoma tissue." (PMID 28147335, 2017). "MCAM promoter methylation was directly correlated with tumor stage in primary prostate carcinoma." (PMID 41388158, 2025). "Since MCAM has a positive effect on cancer metastasis, studies have demonstrated that MCAM knockdown can reduce lytic bone metastasis in preclinical mouse models of prostate cancer, and MCAM-targeted mAbs can effectively postpone intraosseous metastatic lesions." (PMID 37701037, 2023). "Western blotting and quantitative reverse transcription-PCR validation revealed a higher abundance of CD146 (MCAM) in PC-3 exosomes, indicating that aggressive prostate cancer exhibits elevated levels of adhesion or cohesion proteins." (PMID 40230419, 2025). "In this study, we selected six genes, that had additionally been independently reported to be related to prostate cancer progression, CAV1, COL4A2, HSPB1, ITGB3, MAP1A and MCAM." (PMID 26158290, 2015). "The MCAM gene promoter was also shown to be specifically methylated in prostate cancer cell lines and primary prostate cancer but not in non-neoplastic prostate tissues." (PMID 41388158, 2025).
osteosarcoma (26 papers, 2010 to 2025). A usually aggressive malignant bone-forming mesenchymal neoplasm, predominantly affecting adolescents and young adults. "In our study, MCAM was also identified as a key gene associated with angiogenesis and metastasis in tip-like ECs, making it a valuable therapeutic target in osteosarcoma treatment." (PMID 40221534, 2025). "Additionally, elevated MCAM expression was associated with osteosarcoma progression." (PMID 41388158, 2025). "For example, in osteosarcoma studies, spatial transcriptome technology successfully captured the co-localization of MCAM+ tip-like endothelial cells in the “niche” of tumor cells in metastatic lymph nodes, explaining the metastatic propensity of tumors." (PMID 41303611, 2025). "In the case of osteosarcoma, MCAM expression was reported to be significantly higher in biopsies from patients who developed metastases within 5 years compared to those without metastases." (PMID 41388158, 2025). "What’s more, MCAM was highly expressed in tip-like ECs and was likely to promote the metastasis of osteosarcoma." (PMID 40221534, 2025). "In this study, we utilized the GEO and TARGET osteosarcoma (OS) databases and identified melanoma cell adhesion molecule (MCAM), a gene with multiple biological functions in OS pathology, as a novel prognostic biomarker for OS." (PMID 34961985, 2022). "We found CD146 (also known as MCAM or MUC18), can reliability enrich for TPCs in osteosarcoma and UPS." (PMID 26517673, 2015). "MCAM was a functional gene for tip-like ECs and could serve as a target for the treatment of osteosarcoma." (PMID 40221534, 2025). "To investigate whether MCAM influences lymph node metastasis in osteosarcoma, we analyzed its expression in normal (NLNs) and metastatic lymph nodes (MLNs) using scRNA-seq data." (PMID 40221534, 2025). "Additionally, anti-melanoma cell adhesion molecule (MCAM) CAR-NK cells have shown significant antitumor activity in osteosarcoma models, suggesting that targeting MCAM could be a viable strategy for OS immunotherapy." (PMID 40170852, 2025). "METTL3/m6A/IGF2BP1-mediated stabilization of melanoma cell adhesion molecule (MCAM) and zinc-fingers and homeoboxes 2 (Zhx2) mRNA suppressed apoptosis of osteosarcoma cells and RCC cells." (PMID 40584294, 2025). "Both univariate and LASSO Cox regression analyses were conducted on screened module genes to identify 5 GCSRGs (RPS28, MCAM, EN1, TRAM2, and VEGFA) constituting a prognostic signature for osteosarcoma patients." (PMID 36618348, 2022). "In addition, MCAM expression was successively increased in mesenchymal stem cell samples (MSC, n = 4), osteosarcoma stem cell samples (OSC, n = 4), and adherent osteosarcoma cell samples (AOC, n = 4)." (PMID 34961985, 2022).
ovarian carcinoma (21 papers, 2009 to 2025). A malignant neoplasm originating from the surface ovarian epithelium. "In ovarian cancer, the expression of MCAM is associated with a higher risk of early recurrence, as indicated by a shorter time to progression (TTP) and poorer overall survival (OS)." (PMID 41388158, 2025). "MCAM also has been reported to contribute to cancer cell migration and invasion capacity in other solid tumors, including ovarian cancer." (PMID 33371469, 2020). "MCAM is likely to participate in the regulation of the Rho signalling pathway to protect ovarian cancer cells from apoptosis and promote their malignant invasion and metastasis." (PMID 22610942, 2012). "Our results showed that MCAM expression was particularly high in metastatic ovarian cancers compared with other pathological types of ovarian epithelial tissues." (PMID 22610942, 2012). "However, there have been reports of inhibition of cancer metastasis, including in vivo, using MITF inhibitor, MCAM antibodies, and miRNA targeting MCAM; it is hoped that inhibition of the MITF/MCAM axis will inhibit metastasis of ovarian cancer." (PMID 33371469, 2020). "Following the definition of key regulators, we could able to identify five KRs, namely, AKT1, KRAS, EPCAM, CD44 and MCAM, that are key regulators (organizers) of the ovarian cancer network." (PMID 31752757, 2019). "Therefore, MCAM can be used not only as a molecular marker to determine the prognosis of ovarian cancer but also as a therapeutic target in metastatic ovarian cancer." (PMID 22610942, 2012). "Furthermore, we found that when MCAM was silenced, the growth of the ovarian cancer cell lines SKOV-3 and OVCA-429 were significantly inhibited." (PMID 22610942, 2012). "The findings above suggest that MCAM plays an important role in protecting epithelial ovarian cancer cell from apoptosis and promoting their metastasis, indicating that MCAM can be used as a potential target for the clinical treatment of epithelial ovarian cancer." (PMID 22610942, 2012). "Taken together, MCAM might regulate the Rho signalling pathway to promote ovarian cancer cell malignant invasion and metastasis and protect them from apoptosis." (PMID 22610942, 2012). "It is noteworthy that the MCAM-positive rate is especially high in metastatic ovarian cancer lesions, indicating that MCAM expression may be involved in the metastasis of ovarian cancer." (PMID 22610942, 2012). "Therefore, MCAM silencing mainly affected the ability of ovarian cancer cells to spread in the matrix protein." (PMID 22610942, 2012). "Our study has demonstrated that MCAM affects ovarian cancer cell apoptosis and invasion, indicating that, in addition to being used as a molecular marker to determine the prognosis of ovarian cancer, MCAM may also be used as a new target for clinical treatment." (PMID 22610942, 2012). "In conclusion, we have demonstrated that MCAM have multiple effects on epithelial ovarian cancer cell properties, including invasion, apoptosis and spreading on extracellular matrix, which may be related to the dysregulation of small Rho GTPase (RhoA and Cdc42)." (PMID 22610942, 2012). "We examined the cell proliferation and apoptosis and found that the apoptosis of ovarian cancer cell lines SKOV-3 and OVCA-429 were increased by silencing of MCAM." (PMID 22610942, 2012). "In ovarian cancer network, out of seventy leading hubs in the ovarian cancer network, we could able to explore five such KRs which are AKT1, CD44, MCAM, KRAS and EPCAM." (PMID 31752757, 2019). "The role of MCAM in ovarian cancer development has not been fully studied." (PMID 22610942, 2012). "However, no studies have investigated how MCAM expression is regulated in ovarian cancer cells." (PMID 33371469, 2020).